SIRT3 (sirtuin 3)
Diseases named in the same sentence as SIRT3 in open-access papers (continued):
Sharing a sentence is not in itself a finding about the gene and the disease.
gastric cancer (continued). "Our results suggested that 4-BR inhibited gastric cancer cell stemness through the SIRT3-c-Jun N-terminal kinase pathway and may aid in gastric cancer stem-cell–targeted therapy." (PMID 35723384, 2021). "4-BR may utilize the SIRT3-JNK-mediated pathway to downregulate gastric cancer stemness and increase chemosensitivity." (PMID 35723384, 2021). "SIRT3 promotes cellular proliferation and may be involved in 5-FU-induced autophagy, epithelial-mesenchymal transition, and chemoresistance in gastric cancer cells." (PMID 35723384, 2021). "Recent studies have shown that Sirt3 could downregulate Notch1 in human gastric cancer, and Notch1 overexpression attenuated the inhibitory effect of Sirt3 on the proliferation of tumor cells." (PMID 29311941, 2017). "We sought to investigate whether SIRT3 knockdown plays a role in the progression of gastric cancer using established gastric epithelial cell lines." (PMID 29108235, 2017). "SIRT3 may be a valuable effector molecule for gastric cancer prevention, as well as a potential treatment strategy." (PMID 29108235, 2017). "We were then wondering how cellular bioenergetics could be altered in SIRT3-overexpressing gastric cancer cells." (PMID 26121691, 2015). "In addition, a study revealed that SIRT3 participated in the mitochondrial metabolic balance of gastric cancer and promoted deacetylation and activation of LDHA, thereby enhancing glycolysis and proliferation of gastric cancer, and was considered a cancer promoting factor." (PMID 40421455, 2025). "In addition, overexpression of SIRT3 significantly inhibited the proliferation ability and colony formation number of gastric cancer cells by downregulating Notch-1, and inhibited the proliferation of gastric cancer cells." (PMID 40943150, 2025). "In addition, as a key protein regulating anaerobic glycolysis, lactate dehydrogenase A (LDHA) could be deacetylated and activated by SIRT3 to promote glycolysis and increase ATP production in gastric cancer cells." (PMID 35832551, 2022). "However, another study showed that SIRT3 can function as a tumor suppressor in gastric cancer." (PMID 35571098, 2022). "SIRT3 may provide a novel therapeutic option for gastric cancer." (PMID 35723384, 2021). "However, the mechanism by which stemness is regulated through SIRT3 inhibition in gastric cancer remains unknown." (PMID 35723384, 2021). "Univariate Cox regression analysis revealed that HDAC1, HDAC5, HDAC8, SIRT3, and SIRT6 were significant predictors of gastric cancer." (PMID 37649598, 2023). "It has been reported that SIRT3 can promote lactate dehydrogenase A (LDHA) deacetylation and activation to enhance glycolysis and proliferation in gastric cancer." (PMID 35571098, 2022). "The expression of SIRT3 was aberrantly decreased in head and neck squamous cell carcinoma (HNSCC), gastric cancer, and mantle cell lymphoma." (PMID 31113446, 2019). "SIRT3 also plays a role in gastric cancer (GC); however, its role in the pathogenesis of GC remains unclear." (PMID 27686535, 2017). "This study was designed to answer the question whether the tumor suppressor SIRT3 protein influences ROS production and HIF-1α activity in H. pylori-infected gastric cancer cells." (PMID 29108235, 2017). "We found that, in gastric cancer cells, LDHA activity was significantly increased in SIRT3 overexpressing cells, whereas decreased in SIRT3 knockdown cells compared to NC or Scr control cells separately without detectable change in LDHA protein level in the stable transfectants." (PMID 26121691, 2015). "Immunohistochemistry analysis in tumor and adjacent non-tumor normal tissues from a group of gastric cancer patients demonstrated that SIRT3-positive cells were more frequently detectable in tumor tissues than that in normal tissues." (PMID 26121691, 2015). "However, the inhibition of SIRT3 activity involved in gastric cancer stemness and chemoresistance has not been thoroughly explored." (PMID 35723384, 2021).
liver fibrosis (22 papers, 2018 to 2026). "In hepatic fibrosis models, SIRT3 has been implicated in mediating the anti-fibrotic effects of withaferin A134, an effect that is abolished in SIRT3-knockout mice." (PMID 40860195, 2025). "Studies have elucidated that SIRT3 deficiency can aggravate liver injury while SIRT3 activation led to alleviate liver fibrosis." (PMID 38765810, 2024). "Consistently, Sirt3-overexpressing transgenic mice have attenuated liver fibrosis associated with reduced SMAD3 protein levels in liver tissues, therefore SIRT3 plays a role in regulating TGFβ signaling." (PMID 33086678, 2020). "Previous reports suggested that SIRT3 was involved in the occurrence and development of liver-associated diseases including liver fibrosis." (PMID 33029279, 2020). "SIRT3 plays a key role in the development of liver disease and is expected to be a potential target for the prevention and treatment of liver fibrosis." (PMID 39859490, 2025). "In brief, PSG can reduce inflammatory response by regulating SIRT3-mediated NF-κB P65 expression in liver fibrosis, which is an effective anti-fibrotic effect." (PMID 38294557, 2024). "WFA inhibited liver fibrosis through the inhibition of oxidative stress in a SIRT3-dependent manner." (PMID 37196115, 2023). "By activating AMPK/Sirtuins (SIRT3) signaling pathway, hesperetin derivative-16 (HD-16) can increase SIRT3 expression in liver fibrosis." (PMID 38202710, 2023). "Celastrol, a pentacyclic triterpene extracted from Tripterygium wilfordii, can effectively improve the activation of hematopoietic stem cells and liver fibrosis by increasing SIRT3 promoter activity and SIRT3 expression." (PMID 37196115, 2023). "Intriguingly, treatment with compound C (an AMPK inhibitor) or AMPK1α siRNA significantly inhibited SIRT3 expression, suggesting that celastrol attenuates liver fibrosis primarily by activating the AMPK-SIRT3 signaling pathway to inhibit inflammation." (PMID 37196115, 2023). "In the present study, DPx induced upregulations of SIRT1 and SIRT3 by DPx showed amelioration of TAA-induced liver fibrosis." (PMID 37324954, 2023). "Another study showed that AMPK silencing suppressed SIRT3 expression in vitro and in vivo, indicating that AMPK was an upstream target of SIRT3 in liver fibrosis." (PMID 37196115, 2023). "Altogether, SIRT3 was essential for the antioxidant effect of WFA in CCl4-induced liver fibrosis in mice." (PMID 33029279, 2020). "As oxidative stress is often concomitant with the development of liver fibrosis, we then studied the effect of SIRT3 silencing on oxidative stress regulated by WFA." (PMID 33029279, 2020). "To further study the critical role of SIRT3 in mediating the protection effect of celastrol on liver fibrosis, we then examined the effect of SIRT3 depletion on AMPK‐PGC‐1α signalling in activated HSCs." (PMID 31742890, 2020). "Our study suggested that WFA inhibited liver fibrosis through the inhibition of oxidative stress in a SIRT3-dependent manner." (PMID 33029279, 2020). "The current study is aimed at investigating the role of SIRT3 in WFA-induced antioxidant effects in liver fibrosis." (PMID 33029279, 2020). "Studies found that SIRT3 deficiency aggravated the carbon tetrachloride- (CCl4-) induced liver injury, while activation of SIRT3 contributed to the attenuation of liver fibrosis." (PMID 33029279, 2020). "WFA promoted the SIRT3 expression, while depletion or knockout of SIRT3 ameliorated the antioxidant effect of WFA in liver fibrosis." (PMID 33029279, 2020). "In summary, we demonstrated that WFA attenuated the liver fibrosis by inhibiting oxidative stress in a SIRT3-dependent manner." (PMID 33029279, 2020). "Sirtuin 3 (SIRT3) is a deacetylase involved in the development of many inflammation-related diseases including liver fibrosis." (PMID 33029279, 2020). "SIRT3 overexpression can restore liver function, inhibit inflammation and apoptosis, and alleviate liver fibrosis." (PMID 32724473, 2020).
liver fibrosis (continued). "In addition, SIRT3 has a role in liver fibrosis, thus is a potential therapeutic approach for its treatment." (PMID 39859490, 2025). "It was reported that WA led to decrease of liver fibrosis in a SIRT3-dependent manner." (PMID 38765810, 2024). "The overexpression of SIRT3 protects liver function and alleviates liver fibrosis." (PMID 38202710, 2023). "There is evidence that SIRT3 plays a protective role in liver fibrosis by regulating mitophagy." (PMID 38202710, 2023). "Celastrol protects against CCl4-induced hepatic fibrosis through activating AMPK/SIRT3 signaling." (PMID 37005411, 2023). "The role of SIRT3 in liver fibrosis is less known, although SIRT3 activators may weaken the expression of fibrosis-related proteins, such as HMGB-1, type 1 collagen, and alpha-SMA." (PMID 34899370, 2021). "Therefore, SIRT3 KO mice were further used to elucidate the role of SIRT3 in WFA-induced liver fibrosis in mice." (PMID 33029279, 2020). "Moreover, SIRT3 overexpression protected hepatic function, attenuated liver fibrosis, alleviated the inflammatory response, and prevented hepatocyte apoptosis, making SIRT3 a potential therapeutic target for the treatment of nonalcoholic fatty liver disease." (PMID 33029279, 2020). "Overall, SIRT3 is crucial for the anti‐inflammatory role of celastrol in liver fibrosis." (PMID 31742890, 2020). "Another important point is that TGF‐β is considered as the key promoting factor in liver fibrosis, as celastrol could up‐regulate SIRT3, whether there is a regulatory role between SIRT3 and TGF‐β?" (PMID 31742890, 2020). "SIRT3 siRNA attenuated the anti-inflammation effect of celastrol in liver fibrosis." (PMID 33029279, 2020). "AMPK‐PGC‐1α signalling involved in regulating SIRT3.33, 34 Thus, whether activation of AMPK‐PGC‐1α participated in the regulation of SIRT3 in liver fibrosis was further investigated." (PMID 31742890, 2020). "Furthermore, SIRT3 inhibits the activation of hepatic stellate cells (HSCs) by mediating the downstream signaling pathway of transforming growth factor-β (TGF-β)-Smad in liver fibrosis." (PMID 39859490, 2025). "Moreover, further study demonstrated that SIRT3 disruption suppressed the secretion and expressions of inflammatory cytokines and improved the inflammatory microenvironment in liver fibrosis, indicating that SIRT3 intervene attenuated the anti‐inflammatory effect of celastrol." (PMID 31742890, 2020). "One study showed that increasing SIRT3 expression in HSCs with adenoviral transfection or supplementation of resveratrol in methionine choline deficient (MCD) diet-fed mice led to a decrease in HSCs activation and alleviated hepatic fibrosis through the SDH-succinate-GPR91 pathway in vivo." (PMID 30186230, 2018). "Sirtuin 3 (SIRT3) is a deacetylase enzyme that plays a critical role in developing numerous inflammatory diseases, such as liver fibrosis." (PMID 38794167, 2024). "Our study verified that WFA attenuated platelet-derived growth factor BB- (PDGF-BB-) induced liver fibrosis and promoted PDGF-BB-induced SIRT3 activity and expression in JS1 cells." (PMID 33029279, 2020). "Sirt3 plays an important role in regulating lipid homeostasis by ameliorating HFD-induced inflammation, liver fibrosis, and steatosis." (PMID 32093284, 2020). "ROS promotes liver fibrosis through AKT-mTOR and ERK1/2 signaling, while SIRT3 resists liver fibrosis by eliminating harmful ROS." (PMID 32724473, 2020). "Notably, SIRT3 depletion attenuated the antifibrogenic effect of WFA, suggesting that WFA inhibited liver fibrosis in a SIRT3-dependent manner." (PMID 37196115, 2023). "In addition, recent literature has shown that Sirt3 mediates PSG, an anthraquinone extracted from Japanese sorghum, by reducing the expression of NF-kB in activated HSC, and alleviates liver fibrosis through anti-inflammatory effects." (PMID 34095262, 2021).
liver fibrosis (continued). "In addition, inhibition of AMPK by employing compound C (an AMPK inhibitor) or AMPK1α siRNA significantly suppressed SIRT3 expression, suggesting that AMPK was an up‐stream protein of SIRT3 in liver fibrosis." (PMID 31742890, 2020). "Consistent with the in vitro results, WFA could increase SIRT3 expression and attenuate carbon tetrachloride (CCl4 )-induced liver fibrosis in WT mice but not SIRT3-KO mice." (PMID 37196115, 2023). "However, WFA had no obvious effect on SIRT1 expression but notably increased the SIRT3 expression, suggesting that SIRT3 but not SIRT1 contributed to the preventive effect of WFA on liver fibrosis." (PMID 33029279, 2020). "However, whether regulation of oxidative stress involved in the antifibrogenic effect of WFA, and in particular, whether SIRT3 mediates the antioxidant stress effect of WFA in liver fibrosis has never been evaluated." (PMID 33029279, 2020). "Interestingly, treatment with celastrol increased SIRT3 but not SIRT1 mRNA expression, suggesting that SIRT3 participated in the attenuation effect of celastrol on liver fibrosis." (PMID 31742890, 2020).
Stroke (21 papers, 2016 to 2026). Sudden impairment of blood flow to a part of the brain due to occlusion or rupture of an artery to the brain. "Intriguingly, Sirt3 is a mitochondrial form of the deacetylase, and, as noted, mitochondrial damage is a cause of secondary cell death after stroke." (PMID 36361891, 2022). "Taken together, current research sheds light on the widespread role that SIRT3 activity may play in regulating normal brain function, and how its activities could influence the pathogenic course of stroke and different neurodegenerative diseases." (PMID 30090057, 2018). "In addition, adjudin treatment after stroke promoted functional and neurovascular recovery accompanied with the decreased area of glial scar in WT mice, which was blunted by Sirt3 deficiency." (PMID 29311941, 2017). "In contrast, SLC16A1, SIRT3, PFKP, and TKT were inversely associated with stroke risk, suggesting a potential protective role." (PMID 41877258, 2026). "A decrease in SIRT3 levels was observed in mouse neurons that experienced oxygen-glucose deprivation, mimicking a stroke, followed by reperfusion." (PMID 40724883, 2025). "In SIRT3 knockout mice post-stroke, neuroprotection occurred through a compensatory increase in SIRT1 levels, independent of the loss of SIRT3." (PMID 40356977, 2025). "Changes in the blood-brain barrier directly caused by endothelial injury play a significant role in the pathogenesis of ischaemic stroke, and SIRT3 plays a critical role in alleviating vascular endothelial injury after stroke." (PMID 37009480, 2023). "SIRT3 present in astrocytes and vascular endothelial cells can significantly reduce damage to the blood-brain barrier after brain injury, especially in stroke." (PMID 37009480, 2023). "More research is needed to elucidate the mechanisms of the synergistic effects of SIRT1, SIRT2, and SIRT3 on the protection and death of penumbra cells in stroke." (PMID 35574497, 2022). "Two deacetylases, Sirt1 and Sirt3, are shown to control the blood–brain barrier integrity after stroke." (PMID 36361891, 2022). "For example, Sirt3 knockout male mice are less vulnerable to ischemia/reperfusion or stroke injury, and upregulation of SIRT3 inhibits apoptosis in ischemia-challenged PC12 cells." (PMID 34440058, 2021). "In male SIRT3 KO mice and wild-type littermates (WT), stroke-induced increases in liver kinase 1 (LKB1) activity were also appeared reduced in KO mice at 3 days after stroke." (PMID 32380741, 2020). "The deacetylation activity of SIRT3, measured as the amount of reduced acetylated lysine, was increased after stroke." (PMID 32380741, 2020). "The specific role of SIRT3, a mitochondrial sirtuin, in post-stroke injury has been relatively unexplored." (PMID 32380741, 2020). "Together, these findings demonstrate that stroke modulates SIRT3 expression and activity, although the precise mechanism remains elusive." (PMID 30450031, 2018). "To date, several studies have examined the role of SIRT3 in different in vitro and in vivo models of stroke." (PMID 30090057, 2018). "The pathological condition of stroke involves both metabolic and hypoxic stress, and under these conditions, SIRT3 dynamics are more difficult to explain." (PMID 30450031, 2018). "This suggests that total SIRT3 expression is unchanged after stroke, but its activity is regulated through a mechanism yet to be determined." (PMID 30450031, 2018). "In vivo models of stroke reveal increase SIRT3 activity, as determined by a decrease in protein acetylation, but no significant change in SIRT3 protein level." (PMID 30450031, 2018). "To determine the underlying roles of Sirt3 and adjudin in astrocyte activation after stroke, we used primary astrocytes and performed a mouse model of transient middle cerebral artery occlusion (tMCAO) in wildtype (WT) and Sirt3 knockout (KO) mice." (PMID 29311941, 2017). "Initially, evidence suggested that the deacetylation activity of SIRT3 increases after stroke." (PMID 37009480, 2023).
Stroke (continued). "Recent evidence showed that reduced deacetylase activity of Sirt3 may link mitochondrial dysfunction with the initiation of the inflammatory response during stroke." (PMID 36819779, 2023). "Recent studies have indicated that dysregulation of Sirt3 may link mitochondrial dysfunction with the initiation of the inflammatory response during stroke, and that enhancement of Sirt3 deacetylation activities may prevent these pathological injuries." (PMID 36819779, 2023). "More studies approached the question of SIRT3 involvement in brain damage due to stroke." (PMID 32380741, 2020). "Overall, it was concluded that SIRT3 KO mice show neuroprotection by a compensatory rise in SIRT1 rather than the loss of SIRT3 after stroke." (PMID 32380741, 2020). "Further experiments that address SIRT3 activity when PARP is inhibited in stroke models would uncover whether PAR dependent mitochondrial damage is exacerbated by SIRT3 activity in stroke." (PMID 30450031, 2018). "PARP activation, a major component of stroke pathology could play an important role in SIRT3 regulation." (PMID 30450031, 2018). "Yet, a recent study demonstrates that SIRT3 activity in stroke increases mitochondrial dysfunction." (PMID 30450031, 2018). "Converging data now suggest that augmenting SIRT3 activity may be beneficial in progressive neurodegenerative diseases such as AD and PD, and that modulating SIRT3 activity may also provide protection in different types of stroke depending on context." (PMID 30090057, 2018). "Previous study has shown that adjudin, a potential Sirt3 activator, could attenuate lipopolysaccharide (LPS)- and stroke-induced neuroinflammation." (PMID 29311941, 2017). "However, during stroke when mitochondria are damaged, SIRT3 activity could be detrimental and could exacerbate mitochondrial damage." (PMID 30450031, 2018). "We believe that studies on SIRT3 and PPAR-γ will soon generate new approaches for the treatment of stroke." (PMID 31729962, 2019). "Our study is the first report that indicates Sirt3 might be the downstream target and a novel aspect explaining the beneficial and clinically relevant PPAR-γ effectively in improving neurodegenerative and inflammatory processes during stroke." (PMID 31729962, 2019). "Although both Sirt3 and PPAR-γ are considered as attractive targets for therapies against stroke and other neurological disorders, the full detailed correlation between Sirt3 and PPAR-γ in brain I/R and stroke is still not clear." (PMID 31729962, 2019). "More extended investigation in in vivo models such as animal models is therefore needed to confirm the effect of targeting SIRT3 and PPAR-γ in stroke, especially for the findings are not in agreement between different in vitro models." (PMID 31729962, 2019).